MLKL (mixed lineage kinase domain like pseudokinase)
Diseases named in the same sentence as MLKL in open-access papers (continued):
Sharing a sentence is not in itself a finding about the gene and the disease.
diabetes (8 papers, 2021 to 2026). "Recently, a heterozygous MLKL missense variant p.G316D (rs375490660) was reported to be associated with Maturity Onset Diabetes of the Young (MODY) in a Palestinian family." (PMID 35166320, 2022). "By this same evolutionary logic, MLKL's implication in diseases like diabetes and Alzheimer's also warrants the investigation of any historical survival advantage conferred by MLKL gene variants or expression Quantitative Trait Loci (eQTL) with regards to nutrient acquisition and storage." (PMID 35166320, 2022). "In light of three recent clinical reports linking MLKL loss-of-function mutations to neurodegeneration and diabetes, modeling the impact of prolonged MLKL loss in mice is integral to understand if therapeutic inhibition of MLKL could contribute to the development or progression of human disease." (PMID 36755069, 2023). "Co-staining of p-MLKL and iba1+ microglia using retinal flat-mounts further confirmed that diabetes-induced necroptosis occurs specifically in microglia." (PMID 36991017, 2023). "Nevertheless, the role of MLKL in cardiomyocyte necroptosis and heart dysfunction during diabetes remains elusive." (PMID 36030201, 2022). "To provide further evidence to support the role of MLKL in cardiomyocyte necroptosis in diabetes, we knocked down MLKL in akita type-1 diabetic mouse hearts by systemic delivery of shRNA against MLKL (pshMLKL)." (PMID 36030201, 2022). "Second, the use of a monkey model of type-1 diabetes provided translational evidence that the necroptosis signaling RIPK3 and MLKL are activated in diabetic hearts and may represent new therapeutic targets for cardiac complications of diabetes." (PMID 36030201, 2022). "This study characterized cardiomyocyte necroptosis in diabetic hearts and investigated whether MLKL-mediated necroptosis is a target for cardiac protection in diabetes." (PMID 36030201, 2022). "This MLKL mutation may act as a modifier to the P33T PDX1 mutation, and points to a potential role of impairment of necroptosis in diabetes." (PMID 33795639, 2021). "However, the total protein levels of RIPK3 and MLKL were similar between sham and diabetes groups." (PMID 36030201, 2022). "However, MLKL-G316D substitution, which fully ablates MLKL killing activity in human cells was observed exclusively in diabetic patients, suggesting a potential role of impairment of necroptosis pathway in promoting diabetes." (PMID 39872161, 2022). "MLKL oligomer was observed in STZ-injected but not sham mouse hearts, indicating that diabetes induces MLKL oligomerization in the heart." (PMID 36030201, 2022). "Suggests that the RIP3/MLKL/TRPM7 necroptotic pathway may affect penile tissue function mainly through local effects and does not improve diabetes." (PMID 39329120, 2024).
injury (8 papers, 2019 to 2025). Damage inflicted on the body as the direct or indirect result of an external force, with or without disruption of structural continuity. "Some studies have suggested that multiple signal transduction pathways, such as mammalian target of rapamycin (mTOR), nuclear factor kappa-B (NF-κB), Mixed Lineage Kinase Domain-Like (MLKL), etc., play a role in alcohol-induced brain injury." (PMID 37240148, 2023). "Furthermore, immunochemical staining of RIPK1, RIPK3, and MLKL showed that YQJOF reduces hepatocytic RIPK1, RIPK3, and MLKL levels, which were upregulated in chronic liver injury, acute liver injury, and ACLF model." (PMID 33967802, 2021). "In addition, dabrafenib was found to disrupt the interaction between RIPK3 and MLKL and, consequently, to reduce necroptosis in an acetaminophen-induced liver injury model." (PMID 31817643, 2019). "Hence, MLKL has become a therapeutic target for acute brain injury diseases." (PMID 40079614, 2025). "Interestingly, both pharmacological and alcoholic liver injury were accompanied by MLKL aggregation and S358 phosphorylation, suggesting that MLKL S358 phosphorylation may be one of the biomarkers of liver injury." (PMID 40305291, 2025). "In recent studies, two other MLKL inhibitors were also identified, Ab4B19 (TrkB agonist antibody) and salubrinal (ER stress inhibitor), which were found to exert neuroprotective effects in an I/R cerebral injury mice model through suppressing the levels of MLKL and p-MLKL." (PMID 36361505, 2022).
leukemia (8 papers, 2019 to 2023). A malignant (clonal) hematologic disorder, involving hematopoietic stem cells and characterized by the presence of primitive or atypical myeloid or lymphoid cells in the bone marrow and the blood. "Based on these findings, we postulated that loss of MLKL might benefit leukemia development or progression." (PMID 34079078, 2021). "Staurosporine has been reported to induce RIPK1 and MLKL-dependent necroptotic cell death in leukemia cells when caspase activation is compromised." (PMID 36199434, 2022). "In summary, the loss of MLKL resulted in a marked expansion of primitive myeloid progenitor cells and primitive hematopoietic colonies, which suggested a contribution of MLKL to myeloid progenitor differentiation in leukemia." (PMID 34079078, 2021). "Recently, Staurosporine has been found to trigger RIPK1- and MLKL-dependent necroptosis in leukemia under caspase-compromised conditions." (PMID 33665167, 2020). "Beclin 1-defective leukemia cells were more sensitive to necroptotic stimuli in vitro and in vivo with increased MLKL oligomerization, suggesting that Beclin 1 might be a good target for the treatment of leukemia patients." (PMID 34075202, 2021).
Parkinson disease (8 papers, 2021 to 2025). A progressive degenerative disorder of the central nervous system characterized by loss of dopamine producing neurons in the substantia nigra and the presence of Lewy bodies in the substantia nigra and locus coeruleus. "Some clinical studies have observed significant increases in necroptosis-related genes (NRGs) in postmortem examinations of Parkinson's disease (PD) patients, such as MLKL." (PMID 38149092, 2023). "Furthermore, since hsa-miR-425 boosted MLKL phosphorylation by targeting RIPK1 transcripts, hsa-miR-425-5p depletion was connected to the cellular mechanism of Parkinson's disease." (PMID 35371342, 2022).
periodontitis (8 papers, 2019 to 2025). An acute or chronic inflammatory process that affects the tissues that surround and support the teeth. "Recently, necroptosis, a newly regulated necrosis mediated by the receptor-interacting protein serine-threonine kinases-3 (RIPK3)/mixed lineage kinase domain-like protein (MLKL), is a novel pathogenic mechanism of periodontitis." (PMID 35251521, 2022). "Recent trials indicated that RIPK3 and MLKL-mediated necroptotic cell death played a role in the development of periodontitis." (PMID 37266108, 2023). "In vivo, elevated levels of the necroptosis markers, in particular RIPK1 and MLKL, were observed in gingival tissues collected from patients with untreated chronic periodontitis; but so far, the periodontal ligament cells are supposed to undergo necroptosis." (PMID 32630157, 2020). "Our research demonstrated that CDK9 activation regulated the inflammatory gene transcription and RIPK3-mixed lineage kinase domain-like (MLKL)-mediated necroptosis following P. gingivalis invasion and further influenced the progress of periodontitis." (PMID 31758083, 2019). "We have demonstrated that in an animal model of periodontitis via P. gingivalis infection, the inhibition of MLKL by NSA helps reduce periodontal destruction." (PMID 30814594, 2019). "The level of MLKL in the tissues with periodontitis was almost eight-fold higher than that in normal controls." (PMID 30814594, 2019). "The use of inhibitors of the necroptotic pathway, especially MLKL, might help in the host modulation therapy of chronic periodontitis." (PMID 30814594, 2019). "Low levels of MLKL and pMLKL were observed in the normal control, whereas widespread expression was detected in both the gingival epithelia and connective tissues from chronic periodontitis patients, indicating the presence of necroptosis during periodontitis progression." (PMID 30814594, 2019). "Semiquantitative Western blot analysis showed that RIPK1, pRIPK3, MLKL, pMLKL and FLIPL levels were significantly higher in the chronic periodontitis group than in the normal controls." (PMID 30814594, 2019). "MLKL-mediated necroptosis in macrophages promotes the upregulation of TNF-α, IL-1β, IL-6, COX-2 and MMP9, contributing to alveolar bone resorption in mouse periodontitis models." (PMID 40307566, 2025). "For necroptosis, elevated levels of receptor-interacting protein serine-threonine kinases-1 (RIPK1), phosphorylated RIPK3, mixed lineage kinase domain-like protein (MLKL), and phosphorylated MLKL were observed in gingival tissues collected from patients with untreated chronic periodontitis." (PMID 36836236, 2023). "Notably, elevated levels of RIPK1, phosphorylated RIPK3, MLKL, phosphorylated MLKL, and FLIPL are common in gingival epithelia and connective tissues from CP patients, indicating the presence of necroptosis during progression of periodontitis." (PMID 34970269, 2021).
acute pancreatitis (7 papers, 2017 to 2025). An acute inflammatory process that leads to necrosis of the pancreatic parenchyma. "The authors used knockouts for both RIPK3 and MLKL and showed that RIPK3 deficiency resulted in a more severe pancreatic inflammation and disease, and MLKL deficiency rendered mice even more susceptible to tissue damage caused in the cerulein-induced acute pancreatitis model." (PMID 37409125, 2023). "MLKL deficiency or RIP3 deletion plays a protective role in cerulein–induced acute pancreatitis." (PMID 35281076, 2022). "Among these, previous literature has reported that baicalin can alleviate acute pancreatitis in mice by inhibiting necroptosis through the reduction of phosphorylated MLKL oligomerization." (PMID 40620677, 2025). "In animal models of acute pancreatitis, ischemic injury, and neurodegeneration that are related to RIPK1/RIPK3 deficiency or MLKL knockout, it has been suggested that necroptosis may be a key element in triggering inflammation." (PMID 35276962, 2022). "Additionally, Necroptosis that is dependent upon RIPK3 and MLKL was also shown to worsen tissue inflammation and injury in an acute pancreatitis mouse model." (PMID 29123466, 2017).
hepatocellular carcinoma (7 papers, 2016 to 2024). A malignant tumor that arises from hepatocytes. "A recent study shows that mixed lineage kinase domain-like pseudokinase (MLKL) deficiency in hepatocellular carcinoma cells restricts ER Mg2+ release and mitochondrial Mg2+ uptake, leading to ER dysfunction, mitochondrial oxidative stress, and, ultimately, metabolic-stress-induced parthanatos." (PMID 38799433, 2024). "Necroptosis related proteins RIPK1, RIPK3 and MLKL were highly expressed in hepatocellular carcinoma cells and tumor tissues with Sorafenib treatment, which means that Sorafenib activated the necroptosis pathway in vitro and in vivo." (PMID 33440739, 2021). "Recently, it is increasingly noted that RIPK3 is intrinsically silenced in hepatocytes, raising a question about the role of MLKL in hepatocellular carcinoma (HCC)." (PMID 36650126, 2023). "In hepatocellular carcinoma (HCC) patients, increased RIPK1, RIPK3, and phosphorylated MLKL levels were positively correlated with increases in tumor-infiltrating CD3+ and CD8+ T-lymphocytes." (PMID 38799433, 2024).
influenza (7 papers, 2019 to 2026). An acute viral infection of the respiratory tract, occurring in isolated cases, in epidemics, or in pandemics; it is caused by serologically different strains of viruses (influenzaviruses) designated A, B, and C, has a 3-day incubation period, and usually lasts for 3 to 10 days. "recently reported that inhibition of necroptosis by UH15-38, a RIPK3-specific inhibitor, or by MLKL deficiency, blocks H1N1 virus (PR8)-induced lung injury in a mouse model of severe influenza." (PMID 39811662, 2025). "During influenza A virus (IAV) infection, ZBP1 protein expression, NLRP3 inflammasome, caspase-1, caspase-8, caspase-3, and mixed lineage kinase domain like pseudokinase (MLKL) activation were decreased in IRF1-defective cells." (PMID 39384770, 2024). "In the context of influenza infection, the innate immune sensor ZBP1 is emerging as a key regulator of the concurrent induction of NLRP3-dependent pyroptosis, mixed-lineage kinase domain-like pseudokinase (MLKL)-dependent necroptosis, and CASP8-dependent apoptosis." (PMID 32152420, 2020). "Cleaved-PARP1 increased dose-dependently, while p-MLKL and cleaved-GSDMD showed no consistent trends, indicating that apoptosis was the major pathway triggered by influenza infection in A549 cells." (PMID 41258714, 2026). "While necroptosis was suggested to perform such a role upon infection with Influenza, MNV did not provoke MLKL-mediated membrane permeability but rather induced GSDMD-mediated pyroptosis." (PMID 31017981, 2019).
liver cancer (7 papers, 2020 to 2026). An epithelial or non-epithelial malignant neoplasm that arises from the liver. "Liver cancer cells are also shown to prevent MLKL-mediated necroptosis by epigenetic silencing of Ripk3." (PMID 38474061, 2024). "In addition, it has been proved that some drugs inhibited the progression of liver cancer through PIPK1/PIPK3/MLKL signal." (PMID 36110223, 2022). "Moreover, knockdown of HABON increased RIPK1 and MLKL expression as well as their phosphorylation level in SMMC-7721 and Huh7 liver cancer cells." (PMID 35387966, 2022).
pancreatic adenocarcinoma (7 papers, 2018 to 2025). "The expression of RIPK1, RIPK3, and MLKL was also reported to be upregulated in pancreatic adenocarcinoma (PDA)." (PMID 31914150, 2020). "Interestingly, in the murine pancreatic adenocarcinoma model Panc02.OVA with high susceptibility to ICI, tumor-intrinsic MLKL deficiency did not impact anti-CTLA-4-mediated tumor control and had only minor negative effects on tumor-bearing mice undergoing anti-PD-1 monotherapy." (PMID 40345706, 2025).
systemic inflammatory response syndrome (7 papers, 2020 to 2024). SIRS is a serious condition related to systemic inflammation, organ dysfunction, and organ failure. "In turn, loss of MLKL or RIPK3 protected mice from TNF‐induced systemic inflammatory response syndrome (SIRS)." (PMID 33314666, 2020). "In a mouse model of systemic inflammatory response syndrome (SIRS), the combined loss of MLKL (or RIPK3) and caspase-8 provides significant protection, suggesting that necroptosis and apoptosis coexist in the inflammation mechanism." (PMID 34594225, 2021). "TNF-induced systemic inflammatory response syndrome (SIRS) is the most used models for proving the roles in necroptosis as RIPK3 or MLKL KO mice are resistant." (PMID 35217652, 2022). "Moreover, mice with kinase-dead RIPK1 knock-in mutations are resistant to TNF-induced necroptosis and systemic inflammatory response syndrome (SIRS), similar to RIPK3 knockout mice, and demonstrate superior resistance compared to MLKL knockout mice." (PMID 39062098, 2024).
Arthritis (6 papers, 2015 to 2025). Inflammation of a joint. "In A20-deficient macrophages, MLKL facilitates the LPS-induced release of IL-1β, and in vivo experiments indicate that necroptosis plays an important role in inflammasome-dependent arthritis." (PMID 36522335, 2022). "For instance, the expression levels of RIPK1, RIPK3, and phosphorylated MLKL (p-MLKL) were elevated in both an in vivo arthritis experimental animal model and in vitro acid-induced chondrocytes." (PMID 39600708, 2024). "Surprisingly, MLKL was redundant for arthritis development or resolution in this context." (PMID 33924766, 2021). "Although dependent on RIPK3, this mechanism occurs independent of necroptosis, since MLKL deficiency did not alter arthritis pathogenesis." (PMID 25693118, 2015). "Collectively, these data document substantial in vivo evidence that the clinical chronicity of K/B × N arthritis is dependent on a TLR–TRIF–RIPK3–IL-1β axis that occurs independent of the RIPK3 substrate and essential necroptotic effector, MLKL." (PMID 25693118, 2015). "RIP3 deletion affords more protection than MLKL deficiency in mouse models of renal injury, metastatic tumor, TNF-α challenge, arthritis and infection, supporting other non-necroptotic roles for RIP316,63–65." (PMID 31690718, 2019). "Considering IAPs regulate RIPK3 activity, and suppress K/B × N arthritis severity, we sought to determine if a TLR–TRIF–RIPK3 axis could regulate K/B × N arthritis via caspase-8 or MLKL signalling." (PMID 25693118, 2015). "Consistent with in vitro experiments, interleukin-1 (IL-1)-dependent autoantibody-mediated arthritis is exacerbated in mice lacking IAPs, and is reduced by deletion of RIPK3, but not MLKL." (PMID 25693118, 2015).
cognitive deficits (6 papers, 2021 to 2025). "Pharmacological and genetic inhibition of RIPK1/3 and MLKL have effectively ameliorated pathological changes and cognitive deficits in AD animal models." (PMID 40787447, 2025). "In doxorubicin (DOX)-impaired rats, galangin significantly mitigates cognitive impairment and neurotoxicity via the NOX-1/Nrf-2/HMGB1/TLR4 and TNF-α/MAPKs/RIPK/MLKL/BDNF pathways." (PMID 36015161, 2022). "RIPK3−/−, but not MLKL−/− mice, were protected against postinjury motor and cognitive deficits at 1–4 weeks (RIPK3−/− vs WT: p < 0.05 for group in wire grip, Morris water maze hidden platform trials, p < 0.05 for novel object recognition test, p < 0.01 for rotarod test)." (PMID 34753914, 2021).
HCMV infection (6 papers, 2020 to 2025). "Studies have found that MLKL expression is significantly reduced in fibroblasts 48 h after HCMV infection." (PMID 41156609, 2025). "HCMV infection rapidly stimulates autophagy to block the execution of necroptosis by preventing activated RIPK3 from phosphorylating MLKL." (PMID 41190811, 2025). "As previously noted, pUL36 can inhibit both caspase-8–dependent apoptosis and MLKL-mediated necroptosis, making it a dual-function inhibitor of programmed cell death and a potentially valuable therapeutic target in HCMV infection." (PMID 41156609, 2025). "We found HCMV infection increased the percent of MLKL (pink) localized to the nuclei (blue) of infected monocytes when compared to uninfected cells." (PMID 41190811, 2025). "The effector of necroptosis MLKL was the most significantly down-regulated protein at 48 h of HCMV infection and was among proteins most significantly rescued by addition of MG132." (PMID 32690704, 2020). "Here, a systematic examination of protein degradation at 48 h of HCMV infection determined that degradation of MLKL was sustained throughout early and late infection." (PMID 32690704, 2020). "Thus, both increased cFLIP abundance and MLKL sequestration following HCMV infection are equally necessary for the survival of infected monocytes by preventing the sequential initiation of apoptosis and necroptosis." (PMID 41190811, 2025). "For example, TLR3-induced necroptosis in fibroblasts and endothelial cells did not require RIPK1 but involved both RIPK3 and MLKL, whilst necroptosis due to cytomegalovirus infection was RIPK1-independent but involved RIPK3 activity." (PMID 33925729, 2021). "Moreover, HCMV pUL36 is regarded as a multifunctional inhibitor that can degrade mixed-lineage kinase domain-like protein (MLKL), prevent proteolytic activation of procaspase-8, and then suppress both necroptosis and apoptosis during HCMV infection." (PMID 33921122, 2021).
heart failure (6 papers, 2019 to 2025). Inability of the heart to pump blood at an adequate rate to meet tissue metabolic requirements. "Besides, inhibition of RIP3 and MLKL activation attenuates heart failure." (PMID 35464769, 2022). "For example, the knockout of RIPK3 endowed the mice with the ability to resist heart failure that was triggered by ischemia/reperfusion, and this was independent of the activation of RIPK1 or MLKL." (PMID 31248365, 2019).